PPARA (peroxisome proliferator activated receptor alpha)
Diseases named in the same sentence as PPARA in open-access papers (continued):
Sharing a sentence is not in itself a finding about the gene and the disease.
type 2 diabetes (244 papers, 2005 to 2026). "Dual PPARα/γ agonists that were developed to target hyperlipidaemia and hyperglycaemia in type 2 diabetes patients, caused cardiac dysfunction or other adverse effects as fluid retention and body-weight gain." (PMID 31939313, 2020). "In parallel with the important biological roles of PPARα, PPARγ has also been recognized as a therapeutic target to treat hyperglycemia associated with metabolic syndrome and type 2 diabetes." (PMID 26225954, 2015). "We therefore sought to determine the effect of PPARA gene variation on susceptibility to myocardial infarction in patients with type 2 diabetes." (PMID 16309557, 2005). "We have confirmed the potential importance of genetic variation at the PPARA locus in modulating susceptibility to cardiovascular disease, and have shown that this association is relevant to individuals with type 2 diabetes." (PMID 16309557, 2005). "PPARα agonists lower plasma lipid levels, decrease intrahepatic and muscle lipid accumulation, normalize glucose and insulin levels, and reduce the risk of type 2 diabetes in rodent models." (PMID 20825652, 2010). "Individuals with type 2 diabetes are however particularly susceptible to atherosclerotic macrovascular disease, and PPARα activators such as the fibrate group of drugs appear to be particularly beneficial in reducing cardiovascular events in this group of patients." (PMID 16309557, 2005). "Thus, the PPARA gene is a strong candidate for a genetic determinant of CVD risk in people with type 2 diabetes." (PMID 16309557, 2005). "Obesity is a major risk factor in the development of type 2 diabetes and PPARα may affect body weight through regulation of fatty acid catabolism or expending energy." (PMID 15634355, 2005). "Clinically, PPARγ agonists Such as TZDs Like pioglitazone and rosiglitazone are used to treat type 2 diabetes, while PPARα agonists like fibrates target hyperlipidemia and cardiovascular risks." (PMID 40926269, 2025). "The results of our meta-analysis demonstrated that treatment with PPARα/γ agonist, tesaglitazar, plus metformin reduced triglyceride (TG) concentrations in patients with type 2 diabetes, as compared to metformin treatment alone." (PMID 38627464, 2024). "Fibrates (PPARα agonists) are used to treat dyslipidemia, and thiazolidinediones (PPARγ agonists) are used to increase insulin sensitivity in type 2 diabetics." (PMID 36902313, 2023). "In recent decades, several clinical trials demonstrated the beneficial effects of fenofibrate, a PPARα agonist, on type 2 diabetic patients, including decreases in creatinine clearance and estimated glomerular filtration rate (eGFR)." (PMID 36091833, 2022). "PPARδ is the less studied receptor of this group while PPARα and PPARγ have been extensively investigated as therapeutic targets especially in metabolic diseases like type 2 diabetes (T2D)." (PMID 36176461, 2022). "PPARα agonists (e.g., fibrates) or PPARr agonists (e.g., thiazolidinedione) play important roles in the treatment of hyperlipidemia and type 2 diabetes in the clinic." (PMID 33496266, 2021). "At the metabolic individual level, a defective reabsorption in the proximal tubule, peroxisomal stress and PPARα activity have been related to increased levels of urinary pipecolic acid in type 2 diabetes." (PMID 34356333, 2021). "Another approach for the same problem is using PPARα/δ dual agonists, such as GFT505, which have been shown to treat type 2 diabetes while altogether avoiding the cardiovascular risk of PPARγ agonists." (PMID 35003101, 2021). "Recently, two large, prospective clinical trials have demonstrated that fenofibrate, a canonical synthetic PPARα agonist, has protective effects against DR in type 2 diabetes patients." (PMID 32616724, 2020). "Large clinical trials and several reports revealed that PPARα activation by an agonist has protective effects against DR in type 2 diabetes patients, although the mechanisms of action of the PPARα agonist were unclear." (PMID 32616724, 2020).
type 2 diabetes (continued). "PPARα and PPARγ agonists are already in clinical use for the treatment of hyperlipidemia and type 2 diabetes, respectively." (PMID 33126411, 2020). "Although some candidates showed potential side effects, indeglitazar, developed as a full agonist of PPARα and a partial agonist of PPARγ, has progressed to phase II trials for Type 2 diabetes (T2D)." (PMID 32752136, 2020). "Because of its beneficial effects on glucose and lipid abnormalities in patients with type 2 diabetes, PPARα/γ agonist tesaglitazar is a promising candidate for clinical applications." (PMID 31918918, 2020). "It is interesting to mention that another miRNA, miR-21, was found to be overexpressed in the retina of a type 2 diabetes rodent model and at least partially responsible for PPARα downregulation." (PMID 31249556, 2019). "For example, bexarotene and alitretinoin (RXRs), fibrates (PPARα), and thiazolidinediones (PPARγ) are drugs approved for treating cancer, hyperlipidemia, and type 2 diabetes, respectively." (PMID 30148160, 2018). "Particularly, these clinical trials in patients with diabetes type II highlight the striking anti-inflammatory component of PPARα." (PMID 30424016, 2018). "A new dual PPARα and PPARγ agonist known as Saroglitazar, with a higher activity for PPARα and moderate PPARγ activity, has been approved for the treatment of type 2 diabetes in India in order to control diabetic dyslipidemia." (PMID 28243251, 2017). "The PPAR receptors have 3 identified subtypes: PPARα, PPARβ and PPARγ, all of which have been treated as attractive targets for developing drugs to treat type 2 diabetes." (PMID 23119024, 2012). "Amongthe synthetic ligands, fibrates are hypolipidemic compounds that activate PPARα, and TZDs, which selectively activatePPARγ, are hypoglycaemic molecules that areused to treat type 2 diabetes." (PMID 18584037, 2008). "Through PPARα-mediated regulation of inflammatory pathways and cellular metabolism, fenofibrate, PPARα agonist, exhibits combined neuroprotective and antidiabetic properties capable of ameliorating both Alzheimer’s disease pathology and type 2 diabetes complications." (PMID 41009625, 2025). "Given that Klotho ameliorated abnormal lipid metabolism in the liver by upregulating PPARA expression in type 2 diabetic mice, our results suggest that Klotho may improve fatty acid oxidation by regulating PPARA and PPARGC1A expression." (PMID 38584258, 2024). "PPARα agonists such as fibrates have long been clinically used to treat hypertriglyceridemia, whereas PPARγ agonists, such as thiazolidinediones, are approved for type-2 diabetes (T2D)." (PMID 34681249, 2021). "Moreover, peroxisome proliferator-activated receptor (PPARα) induced reactive oxygen species (ROS) is also involved, especially in type 2 diabetes." (PMID 31382970, 2019). "Furthermore, we have attempted to delineate the structure of thiazolidinediones that is vital for the development of next generation PPARγ or PPARα/γ agonists to be used in the treatment of type 2 diabetes." (PMID 28656106, 2017). "A total of eleven of genes were differently expressed in celiac patients compared with disease controls of which CD36, CD38, FOXP1, SELL, PPARA, PPARG, AGT previously associated with type 2 diabetes and AKAP6, NTNG1 with anorexia nervosa remained significant after correction for multiple testing." (PMID 27483138, 2016). "In diabetic rat aortas, treatment with PPARα activators was able to restore the endothelium-dependent relaxations, and activation of PPARα in type 2 diabetic patients displayed improved flow-mediated endothelium-dependent vasodilation as well as attenuation of oxidative stress." (PMID 26649033, 2015). "Although a few drugs that target PPARγ, such as troglitazone, rosiglitazone, and pioglitazone, have been approved for patients with type 2 diabetes, severe adverse effects have led to interest in the discovery of more diverse and novel compounds that target PPARα or PPARγ." (PMID 26225954, 2015).
type 2 diabetes (continued). "Because adiponectin exerts a potent insulin-sensitizing effect by promoting the activation of AMP-activated protein kinase and PPARα in the liver and skeletal muscle, adiponectin may be a novel and promising therapeutic strategy for type 2 diabetes." (PMID 24845824, 2014). "Among several transcription factors associated with PPARα, PGC-1α acts as a ‘molecular switch’ in pathways controlling glucose homeostasis, and may be a critical link in the pathogenesis of type 2 diabetes." (PMID 24801481, 2014). "Moreover, synthetic ligands for PPARα and PPARγ such as fibric acid and thiazolidinediones, have positive effects in human diseases, including type 2 diabetes, metabolic syndrome, obesity and insulin resistance." (PMID 21311715, 2011). "Furthermore, numerous synthetic compounds are used for clinic therapy, such as fibrate family members and TZDs, both of which are able to bind and activate PPARα and PPARγ, respectively, which is being used to treat metabolic disorders, such as hypertriglyceridemia or type 2 diabetes." (PMID 32536865, 2020). "A series of nitrogen heterocycles containing α–ethoxyphenylpropionic acid derivatives were designed as dual PPARα/γ agonist ligands for the treatment of type 2 diabetes (T2D) and its complications." (PMID 31939313, 2020). "NRs such as the GR (dexamethasone), RXR (bexarotene and alitretinoin), PPARα (fibrates), and PPARγ (thiazolidinediones) have already been successfully targeted by approved drugs for treating autoimmunity, cancer, hyperlipidemia, or type 2 diabetes, respectively." (PMID 31139192, 2019). "A long-term study of human patients with type 2 diabetes showed that treatment with the PPARα agonist fenofibrate significantly reduced albuminuria, which could be potentially related to megalin function in the kidney, including its function as an albumin receptor." (PMID 21311715, 2011). "In this review, we address hepatokines identified in the pathogenesis of NAFLD and NASH, including the signaling of FXR/RXR, PPARα/RXRα, adipogenesis, hepatic stellate cell activation/liver fibrosis, AMPK/NF-κB, and type 2 diabetes." (PMID 36267567, 2022). "The combination of Ganmaidazao and Shengmai-Yin decoction is applied as adjuvant therapy for Type II diabetes mellitus via activation of HSL, PPARα, and AMPK/PI3K/AKT, and inhibition of SREBP-1/FAS, influencing insulin sensitivity, and lipid biosynthesis." (PMID 32477116, 2020). "As attractive targets for type 2 diabetes, many PPAR agonists, including PPARα/γ and PPARβ/γ dual agonists, have been designed and synthesized." (PMID 23119024, 2012). "Chiglitazar, an agent currently used for treating type II diabetes has been identifies as a PPAR agonist, significantly induces apoptosis by enhancing the expression of PPARα in HepG2 cells and triggers apoptosis in tumor cells in glioma and mantle cell lymphoma (MCL)." (PMID 37644011, 2023). "Recently, another group also reported that fenofibrate treatment prevented the development of early diabetic retinopathy without induction of PPARα in the retina in a murine model of type 2 diabetes (specifically, db/db mice)." (PMID 33799938, 2021). "In contrast, hypolipidemic drugs such as fibrates that are more potent PPARα agonists appear more effective in subjects with hyperglycemia such as in type 2 diabetes than in nondiabetic dyslipidemics." (PMID 23533380, 2013). "AdipoRon-induced expression of AMPK, PPARα, PGC-1α, and Nrf2 through both AdipoR1 and AdipoR2 are involved in regulating MCT1/2/4 and may support cellular functions by increasing lactate and ATP levels in the sciatic nerve in type 2 diabetic mice." (PMID 40671105, 2025). "The PPARα promoter is hypermethylated, mainly in patients with non-alcoholic fatty liver disease (NAFLD) and patients with type 2 diabetes." (PMID 39062500, 2024).
type 2 diabetes (continued). "In our results, although the mRNA expression of PPARα had no changes, the enhanced mRNA expressions of ACOX1, 3 and mCPT-1 (PPARα targets) represented the activation of PPARα in the type 2 diabetic rat heart." (PMID 23057715, 2012). "Furthermore, it is likely that there will be differential usage of fibrate (as well as other lipid modifying) drugs between individuals with type 2 diabetes and non-diabetic populations which may also influence the lipid levels differentially by PPARα haplotype." (PMID 16309557, 2005). "In addition to reduced triglyceride concentrations, our findings indicate that adding PPARα/γ activator (tesaglitazar) to metformin treatment does not significantly affect the concentrations of TC and LDL-C as compared to the patients with type 2 diabetes who were treated with metformin only." (PMID 38627464, 2024).
hyperlipidemia (201 papers, 2006 to 2026). "As hyperlipidemia is a known risk factor for diabetic neuropathy, PPARα has been explored for its potential therapeutic effects in diabetic corneal neuropathy." (PMID 38993197, 2024). "Nonetheless, PPARα agonists such as fibrate are currently used clinically to treat hyperlipidemia and reduce the risk of CVDs." (PMID 36615764, 2022). "PPARα is involved in the regulation of lipid metabolism, and hyperlipidemia per se is caused by the increased PPARα expression in megakaryocytes but not in platelets." (PMID 36232746, 2022). "Fenofibrate, a selective PPARα agonist, corrects hyperlipidemia by enhancing β-oxidation and causes a reduction in body weight." (PMID 34593018, 2021). "The activation of PPARα stimulates fat consumption by inducing the expression of genes associated with beta-oxidation, resulting in improved hyperlipidemia." (PMID 34593018, 2021). "The relationships between the phenotypes of hyperlipidemia and the regulation mechanism of lipid metabolism indicates that gene PPARA is likely to be associated with AIP." (PMID 31572191, 2019). "PPARα antagonist 2-chloro-5-nitro-N-(pyridyl) benzamide causes hyperlipidemia and consequent disruption in the membranous structures and in the composition of lipid droplets (notably an increase in triglyceride content) in Huh7 cells." (PMID 22966221, 2012). "PPARα and PPARγ ligands have also been shown to play a potential role in suppressing both hyperlipidemia and polyp formation in Apc gene-deficient mice, an animal model for human familial adenomatouspolyposis." (PMID 17389773, 2007). "DBP can activate the PPARα signaling pathway and affect the expression of fatty acid synthase, sterol regulatory element binding proteins, and glycerol-3-phosphate acyltransferase to cause hyperlipidemia and abnormal liver function." (PMID 35778735, 2022). "It was reported that polymorphisms of the PPARA gene were associated with many diseases, such as liver disease, celiac disease, and hyperlipidemia." (PMID 30778304, 2019). "In addition, PPARα variants were associated with hyperlipidemia." (PMID 30778304, 2019). "PPARα is also a key regulator of fatty acid oxidation and can induce spontaneous fatty liver and hyperlipidemia in mice fed a standard diet." (PMID 40717128, 2025). "Certain herbs commonly used in these soups, such as Poria cocos, have been shown to regulate cholesterol homeostasis in hepatocytes via the PPARα pathway, potentially improving hyperlipidaemia and lipid accumulation." (PMID 40823030, 2025). "Fenofibrate, belonging to the fibrate class and acting as a PPARα agonist, is commonly used in clinical settings for the treatment of hyperlipidemia." (PMID 39934809, 2025). "A previous study showed that oral administration of the PPARα agonist fenofibrate, which is widely used to treat hyperlipidemia, prevented the progression of sciatic neuropathy in diabetic mice by activating of the AMPK-related signaling pathway." (PMID 40917479, 2025). "In ApoE−/− mice, dandelion from alcohol extract of Taraxacum officinale enhanced macrophage cholesterol efflux via activating the PPARα/ABCA1 pathway, thereby ameliorating hyperlipidemia and associated inflammation." (PMID 40872505, 2025). "PPARα regulates lipid metabolism, inflammation, and glucose homeostasis and has emerged as a therapeutic target for hyperlipidemia, diabetic microvascular complications, liver diseases (MASH and MAFLD), and pain." (PMID 40867546, 2025). "Fenofibrate, a peroxisome proliferator-activated receptor alpha (PPARα), is a medical drug for hyperlipidemia." (PMID 39408817, 2024). "For example, sea buckthorn flavonoids improve hyperlipidemia by up-regulating PPARα/CPT-1α and PPARγ/ABCA1 signaling pathways." (PMID 38699583, 2024). "Although our results demonstrate that IXN has anti‐hyperlipidemia effects by activating AMPK/PPARα and PI3K/AKT pathways to mitigate lipid accumulation and oxidative stress, it is imperative to recognize certain limitations." (PMID 39619961, 2024).